IGHV3-53 (immunoglobulin heavy variable 3-53)
Description:
V region of the variable domain of immunoglobulin heavy chains that participates in the antigen recognition. Immunoglobulins, also known as antibodies, are membrane-bound or secreted glycoproteins produced by B lymphocytes. In the recognition phase of humoral immunity, the membrane-bound immunoglobulins serve as receptors which, upon binding of a specific antigen, trigger the clonal expansion and differentiation of B lymphocytes into immunoglobulins-secreting plasma cells. Secreted immunoglobulins mediate the effector phase of humoral immunity, which results in the elimination of bound antigens. The antigen binding site is formed by the variable domain of one heavy chain, together with that of its associated light chain. Thus, each immunoglobulin has two antigen binding sites with remarkable affinity for a particular antigen. The variable domains are assembled by a process called V-(D)-J rearrangement and can then be subjected to somatic hypermutations which, after exposure to antigen and selection, allow affinity maturation for a particular antigen.
Synonyms: IGHV353; VH
Tractability: Antibody: its Gene Ontology location is reachable by antibodies, with high confidence; UniProt places it where antibodies can reach, with medium confidence; UniProt predicts a signal peptide or a membrane-spanning region.
Gene: Immunoglobulin variable (V) gene on chromosome 14 (106,592,676 to 106,593,347, reverse strand). Ensembl gene ENSG00000211967.
Subcellular location: Secreted; Cell membrane
Pathways (Reactome):
Immune System: Antigen activates B Cell Receptor (BCR) leading to generation of second messengers; CD22 mediated BCR regulation; Classical antibody-mediated complement activation; FCERI mediated Ca+2 mobilization; FCERI mediated MAPK activation; FCERI mediated NF-kB activation; FCGR activation; Fc epsilon receptor (FCERI) signaling; Immunoregulatory interactions between a Lymphoid and a non-Lymphoid cell; Initial triggering of complement; Regulation of Complement cascade; Regulation of actin dynamics for phagocytic cup formation; Role of LAT2/NTAL/LAB on calcium mobilization; Role of phospholipids in phagocytosis
Disease: FCGR3A-mediated IL10 synthesis; FCGR3A-mediated phagocytosis; Potential therapeutics for SARS
Hemostasis: Cell surface interactions at the vascular wall
Vesicle-mediated transport: Scavenging of heme from plasma
Gene Ontology:
Molecular function: antigen binding
Biological process: immune response; immunoglobulin mediated immune response
Cellular component: extracellular region; plasma membrane
Homologues: Paralogues in human: IGHV3-66 (97% identical), IGHV3-23 (91% identical), IGHV3-64 (87% identical), IGHV3-74 (87% identical), IGHV3-38 (85% identical), IGHV3-64D (85% identical), IGHV3-11 (84% identical), IGHV3-48 (84% identical), IGHV3OR16-10 (84% identical), IGHV3-33 (84% identical), IGHV3-43 (84% identical), IGHV3-7 (84% identical), and 65 more.
Diseases named in the same sentence as IGHV3-53 in open-access papers:
IGHV3-53 is named in the same sentence as 1 disease in open-access papers, as found by Europe PMC text mining. Sharing a sentence is not in itself a finding about the gene and the disease. The quoted sentences say what the papers report.
COVID-19 (2 papers, 2021 to 2023). A disease caused by infection with severe acute respiratory syndrome coronavirus 2. "Monoclonal antibodies (mAbs) encoded by IGHV3-53 (VH3-53) targeting the spike receptor-binding domain (RBD) have been isolated from different COVID-19 patients." (PMID 33944697, 2021).